CLIP2 (CAP-Gly domain containing linker protein 2)
Description:
Seems to link microtubules to dendritic lamellar body (DLB), a membranous organelle predominantly present in bulbous dendritic appendages of neurons linked by dendrodendritic gap junctions. May operate in the control of brain-specific organelle translocations (By similarity).
Synonyms: CLIP-115; CYLN2; KIAA0291; WBSCR3; WBSCR4; WSCR4; CLIP; WSCR3
Tractability: Antibody: the Human Protein Atlas places it where antibodies can reach. PROTAC: ubiquitination databases record sites on it; its protein half-life has been measured.
Gene: Protein-coding gene on chromosome 7 (74,289,407 to 74,405,943, forward strand). Ensembl gene ENSG00000106665.
Subcellular location: Cytoplasm; Cytoplasm, cytoskeleton
Subcellular location (Human Protein Atlas): Golgi apparatus; Plasma membrane
Gene Ontology:
Molecular function: microtubule binding; microtubule plus-end binding
Biological process: cytoplasmic microtubule organization
Cellular component: cell cortex; cytoplasm; microtubule associated complex; microtubule plus-end; nucleus; cytoskeleton; microtubule cytoskeleton
Genetic constraint (gnomAD): Loss-of-function variants: 36 observed, 99.79 expected, observed/expected ratio (o/e) 0.36, 90% interval 0.28 to 0.48. The upper end of that interval is the gene's LOEUF score, 0.48, which puts it in group 2 of 6, group 1 being the genes least tolerant of losing a copy. Missense variants: 1,132 observed, 1,360 expected, observed/expected ratio (o/e) 0.83, 90% interval 0.79 to 0.87. Synonymous variants: 651 observed, 615.4 expected, observed/expected ratio (o/e) 1.06, 90% interval 0.99 to 1.13.
Homologues: Orthologues: chimpanzee CLIP2 (99% identical), macaque CLIP2 (99% identical), dog CLIP2 (92% identical), rat Clip2 (92% identical), mouse Clip2 (92% identical), guinea pig CLIP2 (87% identical), rabbit CLIP2 (84% identical), tropical clawed frog clip2 (73% identical), zebrafish clip2 (62% identical). Paralogues in human: CLIP1 (45% identical), DCTN1 (14% identical), CLIP4 (12% identical), CLIP3 (11% identical).
Diseases named in the same sentence as CLIP2 in open-access papers:
CLIP2 is named in the same sentence as 31 diseases in open-access papers, as found by Europe PMC text mining. Sharing a sentence is not in itself a finding about the gene and the disease. The quoted sentences say what the papers report.
thyroid cancer (3 papers, 2020 to 2024). "In our study we present an optimized preselection approach for genes subjected to gene-association network reconstruction, which was applied to CLIP2 perturbation transcriptome data of a thyroid cancer cell culture model." (PMID 32727620, 2020). "One potential reason may be the very specific focus of this study, which was elucidation of the functional role of CLIP2 in radiation associated thyroid carcinoma, while the interactions in the STRING and Biogrid database originate from various tissue types cell culture models." (PMID 32727620, 2020). "CLIP2 has been proposed as a biomarker for thyroid cancer in several studies on children in the Chernobyl cohort." (PMID 33382739, 2020). "This study presents a functional characterization of the CLIP2 gene derived from a GAN from the thyroid cancer cell line TPC-1 after perturbation of the CLIP2 mRNA expression." (PMID 32727620, 2020). "Gene association networks (GANs) were reconstructed using transcriptome data from the thyroid cancer cell culture model TPC-1 after CLIP2 siRNA knockdown or stable CLIP2 overexpression." (PMID 32727620, 2020). "Further, the CLIP2 radiation marker has the potential to be implemented in the diagnosis of secondary thyroid carcinomas as consequence of medical exposure to ionizing radiation e.g. during radiologic imaging or radiotherapy." (PMID 32727620, 2020). "Considering the rising thyroid cancer incidence rates in western societies, potentially related to medical radiation exposure, the functional characterization of CLIP2 is of relevance and contributes to the knowledge about radiation-induced thyroid malignancies." (PMID 32727620, 2020). "In addition, the increase in chromosomal band 7q11 and specific overexpression of genes such as CLIP2 after exposure to low doses of radiation may be specific molecular markers of thyroid cancer in children." (PMID 38463235, 2024).
William Beuren syndrome (3 papers, 2017 to 2025). "CLIP2 deletion is linked to Williams-Beuren syndrome, but deletion of a single copy alone is insufficient to result in the physical or cognitive characteristics of the disease." (PMID 30744680, 2019).
Diabetes (2 papers, 2021 to 2024). "Furthermore, SNPs within CLIP2 (rs2528994 and rs512023) have demonstrated modest associations with T2D in both the Diabetes Genetics Initiative and the Wellcome Trust Case Control Consortium." (PMID 38915393, 2024). "Interestingly, CLIP2 has been associated as a key gene for diabetes mellitus development." (PMID 34636989, 2021). "Our EWAS identified DNAm candidates known to be modified by diabetes relevant environmental factors including diet and glucose levels (CLIP2, GNAS/GNAS-AS, MEG3)." (PMID 38915393, 2024).
glioblastoma (2 papers, 2017 to 2018). The most malignant astrocytic tumor (WHO grade IV). "The expression levels of circ_COL1A2, circ_PTN, circ_VCAN, circ_PLOD2, circ_SMO, circ_CLIP2, circ_GLIS3, and circ_EPHB4 in glioblastoma (GBM) are significantly higher than those in normal tissues." (PMID 30064463, 2018). "Eight circRNAs, including circ_COL1A2, circ_PTN, circ_VCAN, circ_SMO, circ_PLOD2, circ_GLIS3, circ_EPHB4, and circ_CLIP2 showed significantly higher expression in glioblastoma (GBM) than in normal tissues." (PMID 28969099, 2017).
glioneuronal tumor (2 papers, 2020 to 2024). "Overall, in the context of a CLIP2::MET fusion detected by RNAseq, the molecular findings are most consistent with a CLIP2::MET fusion-positive glioneuronal tumor." (PMID 38650040, 2024). "This is the first case report demonstrating the presence of a CLIP2::MET fusion in two pediatric low-grade glioneuronal tumors (GNT)." (PMID 38650040, 2024). "We report a case of glioneuronal tumor (GNT) with a discovery of novel gene fusion of CLIP2-MET resulting from aberrant chromosome 7 abnormalities." (PMID 32550005, 2020).
lung carcinoma (2 papers, 2022 to 2025). "No recurrent MET fusions were identified, some of the fusion partners included HLA-DRB1-MET (lung cancer), CD47 (lung cancer), CAPZA2 (gastric cancer), AKAP9 (hepatobiliary cancer), CLIP2 (hepatobiliary cancer), and SLC25A19 (ovarian cancer)." (PMID 36369474, 2022). "Interestingly, SplitFusion detected novel fusions that have not been reported previously in lung cancer, including one squamous cell carcinoma with FGFR3::JAKMP1 fusion, one adenocarcinoma with CLIP2::BRAF fusions (two fusion isoforms in one tumor), and one adenocarcinoma with ITPR2::ETV6 fusion." (PMID 40041857, 2025).
papillary thyroid carcinoma (2 papers, 2017 to 2020). "This study presents the gene association network of CLIP2, which has been previously associated with radiation induced papillary thyroid carcinoma (PTC) in young patients." (PMID 32727620, 2020). "This implies a potential clinical relevance of the CLIP2 radiation marker, while its functional role in radiation-induced papillary thyroid carcinoma is of interest." (PMID 32727620, 2020). "CLIP2 was previously identified as a potential marker for radiation induced papillary thyroid carcinoma (PTC) of young patients in the aftermath of the Chernobyl reactor accident." (PMID 32727620, 2020). "The findings point to a function of CLIP2 as a driver gene in radiation-induced papillary thyroid carcinoma." (PMID 28858225, 2017). "Recently, the investigation of papillary thyroid carcinoma from a cohort revealed an overexpression of the CLIP2 gene among young patients exposed to the post-Chernobyl radioiodine fallout at a very young age." (PMID 28858225, 2017).
anaplastic astrocytoma (1 paper, 2022). "One anaplastic astrocytoma with CLIP2:NTRK2 fusion was classified as anaplastic pilocytic astrocytoma (CS 0.62), currently also known as high-grade astrocytoma with piloid features (HGAP)." (PMID 36163281, 2022).
brain tumors (1 paper, 2023). "It is also shown that the HUGO: CLIP2 gene plays a role in brain tumors." (PMID 37427327, 2023).
Intellectual disability (1 paper, 2024). "Furthermore, we identified one patient with a smaller 167.21-kb microdeletion within the WSCR, including EIF4H, LAT2, RFC2, and CLIP2, but not comprising the ELN gene and segregating in the family with non-syndromic intellectual disability." (PMID 39368701, 2024).
sarcopenia (1 paper, 2024). Progressive decline in muscle mass due to aging which results in decreased functional capacity of muscles. "We found that there was more CLIP2 expressed in the skeletal muscle of ageing mice (+1.1‐fold, p < 0.01) and in patients with sarcopenia (+2.5‐fold, p < 0.01) compared to the control group." (PMID 39385717, 2024).
thyroid (1 paper, 2020). "Additionally, the conducted pathway enrichment analysis on the 1st- and 2nd-neighborhod genes of CLIP2 suggest a functional involvement of CLIP2 in the thyroid carcinogenesis." (PMID 32727620, 2020).
tumor (7 papers, 2020 to 2025). "Subsequent whole transcriptome RNA sequencing (RNAseq) analysis of the tumor sample revealed a CLIP2::MET fusion." (PMID 38650040, 2024). "Immunohistochemical staining of consecutive FFPE tumor sections from PTC patients demonstrated co-expression of the CLIP2 and PPIL3 proteins." (PMID 32727620, 2020). "The screening of the GEPIA database revealed that CLIP2 and SH3PXD2A displayed substantial differences in expression between tumour and normal specimens in OC." (PMID 36131789, 2022). "Non-BRAF alterations were detected in four tumor samples consisting of CLIP2:NTRK2, KANK1:NTRK2, RAF1:QKI, and KRAS Q61H." (PMID 36163281, 2022). "According to fold changes of expression level between non-tumor and tumor, representative target genes were CLIP2, TREM1 (miR-26a), SPOCK1 (miR-375), PENK, and ADAMTS16 (miR-1260)." (PMID 32313120, 2020).
cancer (2 papers, 2020 to 2025). A tumor composed of atypical neoplastic, often pleomorphic cells that invade other tissues. "Literature knowledge on the direct interaction partners strongly suggests an association of CLIP2 with cancer relevant processes such as DNA repair, chromosomal instability and promoted proliferation." (PMID 32727620, 2020). "A first functional association of CLIP2 with cancer-related processes such as genomic instability, mitogen-activated protein kinase signaling, and apoptosis, was derived from de novo a network reconstructed network from PTC samples from radiation exposed patients." (PMID 32727620, 2020). "Thus, the genes LOXL3, ADAM19, FBN2, and RND3 are associated with cancer relevant biological processes such as loss of adhesion, proliferation, migration and metastasis and are therefore might be functionally related to CLIP2 in the context of radiation induced PTC-carcinogenesis of PTC." (PMID 32727620, 2020).
infection (1 paper, 2023). The state of being infected such as from the introduction of a foreign agent such as serum, vaccine, antigenic substance or organism. "The expression pattern and immunoprecipitation results suggested that the activity of CLIP2 was continuously regulated in the absence an immune challenge and was more strictly regulated after pathogen infection." (PMID 37851691, 2023). "Furthermore, we systematically investigated how serpin-1a and serpin-6 synergistically regulate CLIP2 to maintain the homeostasis of the Toll pathway under normal and infection conditions." (PMID 37851691, 2023).
CLIP2 also shares sentences with these, for which no sentence is quoted: adenocarcinoma (1 paper); Andersen syndrome (1); astrocytoma (1); autism (1); Autoimmunity (1); Cognitive impairment (1); gastric cancer (1); glioma (1); melanoma (1); neurodevelopmental disorder (1); neurological disease (1); ovarian carcinoma (1); squamous cell carcinoma (1); thyroid tumour (1); Turner syndrome (1); Vascular Ehlers Danlos syndrome (1).